IRF2 (interferon regulatory factor 2)
Diseases named in the same sentence as IRF2 in open-access papers (continued):
Sharing a sentence is not in itself a finding about the gene and the disease.
preeclampsia (1 paper, 2024). Preeclampsia is a hypertensive disorder of pregnancy that is characterized by new-onset hypertension with proteinuria presenting after 20 weeks of gestation, and depending on mild or severe forms may initially present with severe headache, visual disturbances, and hyperreflexia. "Notably, genes upregulated in preeclampsia and recurrent pregnancy loss were enriched with interferon pathway regulators IRF2 and IRF7, which promote NK cytotoxicity." (PMID 39090334, 2024). "For the pregnancy disorder upregulated regulons and target genes, we identified that the predicted dNK2/3-associated IRF2 and IRF7 targets were enriched with preeclampsia upregulated genes (IRF2 LOP p = 9.2 × 10–5, 19-fold; IRF7 EOP/LOP (p = 5.0 × 10–5/5.6 × 10–5), 7.1-fold / 8.6-fold)." (PMID 39090334, 2024). "Notably, the cell surface receptor CD2, which mediates nanotube formation and augments cytotoxicity, is a target of both IRF2 and IRF7 and was found to be upregulated in both preeclampsia and missed abortion." (PMID 39090334, 2024).
prostate carcinoma (1 paper, 2026). A carcinoma that arises from epithelial cells of the prostate gland. "We also show that SKP2 overexpression in prostate cancer PC3 cells increases the protein levels of TWIST1 and the expression of EMT related genes, including FMOD, THY1, NFIL3 and IRF2, leading to a marked increase in migration and invasion." (PMID 41542047, 2026).
ZIKV infection (1 paper, 2021). "IRF2 was up-regulated in ZIKV infection of human iris pigment epithelial cells." (PMID 34930359, 2021). "Our present study also confirmed that ZIKV infection could upregulate the expression level of IRF2." (PMID 34930359, 2021).
tumor (78 papers, 2008 to 2025). "By implementing SCENIC, we found nine tumor–associated GRNs within the PtR and PtRP GEMMs including one defined by Stat1/2 and Irf2/7/9, validating our recent findings on the critical role of JAK/STAT signaling in initiating plasticity." (PMID 38645034, 2024). "In contrast, IRF2-deficient B16 were resistant to anti-PD1 therapy and tumor growth and survival were unaffected relative to untreated IRF2-sufficient tumors." (PMID 39281881, 2024). "In PC, it is reported that IRF2 expression was upregulated and associated with tumor size, differentiation, pathology stage, and survival of the patients." (PMID 35012444, 2022). "Mutations in genes regulating the immune response such as IRF2 may weaken immune surveillance in this inflammatory environment, facilitating tumor formation and progression." (PMID 40514689, 2025). "It found that tumor-associated macrophages had upregulated genes regulated by IRF2, IRF7, IRF9, and STAT2, and downregulated genes regulated by Fos/Jun and IRF8, revealing decreased inflammatory response, TNF-α-induced proliferation, and reactive oxygen species production pathways." (PMID 39034998, 2024). "Furthermore, the combination of IRF2-deficient CD8+ T cells significantly with anti-PDL1 antibody significantly led to the durable tumor control in the mouse model of breast cancer." (PMID 37398660, 2023). "Furthermore, in colorectal cancer, loss of IRF2 expression mediated by oncogenic KRAS promotes the migration of myeloid-derived suppressor cells to the tumor microenvironment driving resistance to anti-PD-1 therapy." (PMID 37809068, 2023). "Particularly, our finding was supported by a previous study which reported that IRF2 expression was upregulated and associated with tumor size, differentiation, pathology stage, and survival of PC patients and knockdown on the expression of IRF2 inhibited cell growth in PC cells." (PMID 35012444, 2022). "Importantly, KRAS can cause immunosuppression in CRC, allowing for tumor progression through inhibiting interferon regulatory factor 2 (IRF2), which results in an increase in the expression of MDSCs, supporting their migration to TME." (PMID 36430176, 2022). "Increased expression of IRF2, GPX4, and TIRAP, for example, has been linked to enhanced susceptibility of tumor cells to chemotherapeutic agents such as TP-3654, nelarabine, S-49076, ZM-336372, XL-147T, and tivantinib." (PMID 40535818, 2025). "We observed a significant decrease in overall tumor burden grossly at 7.5-weeks post-HDTVi and via decreased LW/BW ratio in Irf2-overexpression β-M model." (PMID 39711542, 2024). "It has been well documented that IRF2 expression by CD8+ tumor-infiltrating lymphocytes drives T cell exhaustion, and irf2−/− CD8+ T cells expressed lower levels of inhibitory receptors including PD-1 as compared with WT CD8+ T cells." (PMID 38995014, 2024). "RNA-seq confirmed the overexpression of Irf2 in the β-M-IRF2 mice at the 7.5-week timepoint where less tumor burden was evident." (PMID 39711542, 2024). "Studies of CD8 T cell-dependent skin disease of Irf2−/− mice and of tumor growth resulting from IRF2-dependent CD8 T cell exhaustion concur in showing increased IFN-I–mediated ISG expression in the absence of IRF2, consistent with a repressive role." (PMID 39276937, 2024). "Instead, further molecular genetic testing showed that the tumor harbored a rare EWSR1::CREM fusion combined with a previously unreported IRF2::NTRK3 fusion." (PMID 37274229, 2023). "More importantly, the effects of immunosuppression from persistent IFN-Is and IFN-γ siganling were inhibited in IRF2-deficient CD8+ T cells, resulting to long-term tumor control." (PMID 37398660, 2023).
tumor (continued). "According to this model, in tumor cells, MVP associates with IRF2 and thereby promotes the secretion of pro-tumoral cytokines such as IL-4." (PMID 38264642, 2023). "Deletion of IRF2 in CD8+ T cells increased effector functions to sustain long-term tumour control in response to ICBT." (PMID 37503572, 2023). "Increased expression of IRF-2 can inhibit tumor growth and affect the prognoses of patients by directly regulating AMER-1 transcription in GC and inhibiting the Wnt/β-catenin signaling pathway." (PMID 35115027, 2022). "KPNA2 removal remarkably suppressed OS cell growth, migration, invasion in vitro, and tumor growth in vivo, while IRF2 knockdown exerts an opposing effect." (PMID 36199790, 2022). "Knockdown of IRF2 significantly impaired tumor killing of sorted NK cells at all examined effector to target ratios, while cells of overexpression cultures had a similar cytotoxic capacity as control NK cells." (PMID 36544762, 2022). "This study determined the expression of IRF-2 in GC tissues and adjacent non-tumor tissues using immunohistochemistry (IHC) and explored the predictive value of IRF-2 for the prognoses of GC patients." (PMID 35115027, 2022). "We observed that the levels of IRF2, 6, 7, 8, and 9 were elevated in tumor compared to normal tissues in PC." (PMID 35012444, 2022). "Future work is needed to establish if the induced IRF2 contributes to the depression of Gsdmd in Mll4−/− tumor cells as well." (PMID 36323669, 2022). "Another study has reported that the delivery of interferon regulatory factor 2 (IRF‐2) by CRC‐derived EVs, to macrophages in SLN promotes VEGF‐C secretion, tumour‐associated lymphangiogenesis, and lymphatic metastasis." (PMID 34295457, 2021). "In this study, IRF2 was found to be expressed in OS tissues at a lower level as compared to that in non‐tumour tissues." (PMID 33264494, 2021). "New signaling pathways of interferon regulatory factors 1 (IRF-1) and 2 (IRF-2) and interleukin (IL)-1 family, IL-6, IL-11, IL-18, and interferons (IFNs) have been found within tumor microenvironments." (PMID 32887217, 2020). "In this tumor model, loss of Cdk5 results in persistent expression of IRF2 and IRF2BP2, which likely leads to reduced PD-L1 expression on tumors thereby promoting anti-tumor immunity." (PMID 35582274, 2019). "The results indicated that IRF2 expression was downregulated in tumour tissues, and likely related to tumour size (P=0.080892), but negative correlation with sex and pathological stage." (PMID 28471447, 2017). "Simultaneously, our experimental data revealed that miR-18a-5p significantly promoted NSCLC tumour growth and migration through targeting IRF2." (PMID 28471447, 2017). "This was in agreement with qPCR results that showed a dramatic reduction in IRF2 at 21 days post tumor challenge." (PMID 27277682, 2016). "Our study showed that ARTD9 can inhibit the IFNγ/STAT1-dependent anti-proliferative and pro-apoptotic activities of tumor suppressor IRF1 while simultaneously activating the STAT1/IRF2-mediated anti-apoptotic-pro-survival pathways in HR-subtype DLBCL cells." (PMID 26654227, 2015). "On the contrary, IRF2 has been shown to inhibit transcription of Cd274 on tumor cells." (PMID 40442146, 2025).
tumor (continued). "We identified through unbiased bulk RNA-seq, scRNA-seq, and spatial transcriptomic approaches tumor-cell-intrinsic roles of β-catenin-mediated IRF2 and POU2F1 repression driving an immune-excluded TIME and inert type I/II IFN responses in β-catenin-mutated HCC with in vivo validation." (PMID 40442146, 2025). "Overall, mutated-β-catenin represses IRF2, POU2F1, and likely other TFs, which limits transcription of key signaling molecules (i.e., cytokines and chemokines) important for priming lymphocyte recruitment needed for effective anti-tumor immunity." (PMID 40442146, 2025). "Given our findings, in future studies it will also be of interest to examine whether IRF2 expression levels in tumor biopsies might be a biomarker for subsequent responsiveness to CPI either by itself or with other markers." (PMID 39281881, 2024). "Perhaps how IRF2 expression affects tumor growth depends on the particular cancer." (PMID 39281881, 2024). "We identified through unbiased scRNA-seq and spatial transcriptomic approaches a novel tumor-cell intrinsic role of β-catenin-mediated IRF2 and POU2F1 repression driving an immune excluded TIME and inert type I/II interferon responses in β-catenin-mutated HCC with in vivo validation." (PMID 39711542, 2024). "Overall, mutated-β-catenin represses IRF2, POU2F1, and likely other TFs, which limits transcription of key chemokines and cytokines important for priming recruitment of lymphocytes needed for an effective anti-tumor immunity and ICI response." (PMID 39711542, 2024). "IRF2 induced by IFN-γ-in T cells results in exhaustion in multiple tumour types." (PMID 37503572, 2023). "CCK8, colony formation, wound healing, and Transwell assays were used to assess cell viability, proliferation, and migration in vitro, and in vivo experiments were performed to explore the effects of KPNA2 and interferon regulatory factor-2 (IRF2) on tumor growth." (PMID 36199790, 2022). "IRF2, a constitutive transcription factor pertaining to cancer development, could exert anti-oncogenic activities by regulating tumor cell apoptosis, growth, and drug resistance." (PMID 36341357, 2022). "To investigate whether IRF2/KPNA2 expression is correlated with other molecular alterations in OS, we evaluated several molecules that are associated with EMT in tumor progression." (PMID 36199790, 2022). "These rescuing effects of IRF2 on KPNA2 were also reflected in tumor growth in vivo." (PMID 36199790, 2022). "This underlying mechanism was consistent with a previous report that IRF2 could bind to the miR-1227 promoter, thus inhibiting tumor growth." (PMID 36199790, 2022). "Moreover, one previous study in our lab has shown that miR-18a can significantly promote NSCLC tumor progression by directly targeting IRF2." (PMID 35484993, 2022). "In gastric cancer, evidence suggested that IRF2 could suppress tumor cell invasion and migration via MMP-1 in STAD." (PMID 35012444, 2022). "In vivo, KPNA2 knockdown markedly reduced tumor weight and tumor volumes while IRF2 knockdown promoted tumor growth, and IRF2 knockdown could weaken KPNA2 knockdown-medicated tumor growth inhibition." (PMID 36199790, 2022). "Since AMER-1 acts as a scaffold protein that recruits APC to consist of the β-catenin destruction complex, we believe that IRF-2 functions as a tumor suppressor gene in GC and that the axis of IRF-2-AMER-1/β-catenin plays an important role in the phenotype of cell proliferation." (PMID 35115027, 2022). "The ten pathways in which IRF-2 was most affected by GO analysis included the tumor necrosis factor-mediated signaling pathway and the Wnt/β-catenin signaling pathway, both of which were related to tumor development and progression." (PMID 35115027, 2022). "Since the absolute value of IRF2 coefficient is the largest (-0.419071422539304), we wonder whether it affects the prognosis by regulating the malignant behavior of tumor cells." (PMID 36341357, 2022).
tumor (continued). "Reportedly, IRF2 is a direct target of miR-1290, and up-modulation of IRF2 can partially mitigate the promotion of NSCLC cell proliferation and invasion caused by miR-1290 overexpression, suggesting IRF2 is a tumor suppressor in NSCLC." (PMID 34022918, 2021). "In addition, upon staining the tumour sections to detect IRF2 expression, the results revealed that the IRF2 expression level was also higher in circ‐0000658 group than in Lv‐NC group." (PMID 33264494, 2021). "Thus, while IRF2 expression is downregulated in many different tumor types suggesting potential tumor suppressor roles, other studies proposed pro-tumorigenic functions for IRF2, including via antagonism of IRF1 functions." (PMID 33668131, 2021). "So, a total of 62 and 57 harbored genes were identified in line 63 and 72, respectively, including several immune-, tumor- and disease-related genes, such as interferon regulatory factor 2 (IRF2), suggesting that the CNV in the IRF2 gene is specific to line 72 in this study." (PMID 32677890, 2020). "In various kinds of cancers, IRF2 showed its tumor-suppressive roles, or oncogenic functions." (PMID 30876449, 2019). "In addition, a high IRF-2/IRF-1 protein ratio positively correlates with tumor invasion and metastatic ability in human HCC cell lines." (PMID 29599126, 2018). "Furthermore, a conspicuous upregulation in the expression of miR-18a-5p and decreased IRF2 expression level was observed in tumour tissues from the pLenti-miR-18a group." (PMID 28471447, 2017). "Since IRF2 has oncogenic properties, our data raise the question of whether γHV-induced IRF2 may play a tumor-promoting role during γHV latency." (PMID 22114555, 2011). "Additionally, we demonstrate that forced expression of IRF2 in β-catenin-mutated HCC model is sufficient to convert a non-T cell-inflamed to T cell-inflamed tumor." (PMID 39711542, 2024). "Interferon regulatory factor 2 (IRF2) has been considered a potential tumor protein, which may alter the IFN‐γ/Jak/Stat/IRF pathway through endogenous IFN‐γ, allowing cells to escape growth control mechanisms and promoting stronger invasiveness and faster tumor growth." (PMID 35441810, 2022). "Moreover, IRF2 serve as tumor suppressor and inhibit tumor progression in STAD." (PMID 36045400, 2022). "This is also evident in other studies, where overexpressed IRF2 and downexpressed β-catenin led to decreased BCL2 levels in HCC samples, thus leading to better survival for tumor patients." (PMID 40456804, 2025). "Perhaps this is because the IRF2-deficient tumor cells are able to evade NK cells because they still expresses some MHC I molecules and/or have decreased caspase 7, however further studies are needed to determine whether and to what extent NK cells can recognize and control IRF2-deficient cancers." (PMID 39281881, 2024). "IFN-γ can also activate interferon regulatory factor 2 (IRF2), a CTL transcription factor in the TME, thus changing CTL from an activated state to a depleted state and forcing tumor cells to evade immune surveillance." (PMID 38464516, 2024). "In a word, the roles of IRF1, IRF2, and IRF3 in HCC are complex and bidirectional, exhibiting both tumor-promoting and anti-tumor effects." (PMID 39384770, 2024). "IRF2 also regulated GADD45G, which has been reported to enhance IFNG production and anti-tumor immune effects." (PMID 39090334, 2024). "Another GRN had high activity for IRF2, along with NFATC1/2 and EGR2, consistent with our recent report of tumor–intrinsic inflammatory JAK/STAT signaling and inflammatory programs driving lineage plasticity (labeled as IRF2+ Inflam)." (PMID 38645034, 2024). "For example, IRF1, IRF2, IRF5, IRF8, and IRF9 were found to be upregulated in glioma, and their mRNA levels correlated to the tumor grade and the clinical outcome of the disease." (PMID 37809068, 2023). "We found that the level of IRF2, IRF6, IRF7, IRF8 and IRF9 were upregulated in tumor tissues in PC (P < 0.05)." (PMID 35012444, 2022).